PRSS1 (serine protease 1)
Diseases named in the same sentence as PRSS1 in open-access papers (continued):
Sharing a sentence is not in itself a finding about the gene and the disease.
pancreatitis (continued). "Given the unexplained episode of pancreatitis in a child, it was decided to investigate point mutations in the cationic trypsinogen gene (PRSS1) underlying HP, although no data were available suggesting familial pancreatitis in this patient." (PMID 20950468, 2010). "PRSS1 variant-related pancreatitis can present de novo without affecting family members." (PMID 40230746, 2025). "Because CFTR mutations are not necessarily correlated with the onset of pancreatitis, PRSS1, SPINK1 and CTRC mutations may also lead to pancreatitis." (PMID 36835437, 2023). "However, the reduced penetrance of the mutations in PRSS1 and the absence of other known pathogenic mutations in pancreatitis susceptibility genes in some affected individuals suggest the role of additional yet-undiscovered inherited factors." (PMID 36699452, 2022). "Genetic abnormalities, such as SPINK1, PRSS1, and CFTR gene mutations, are the main risk factors for symptomatic PD in children, and these genetic variants lead to the blockage of the pancreatic duct due to highly viscous pancreatic secretions, inducing pancreatitis in children with PD." (PMID 34796156, 2021). "In a recent cohort from the International Study Group for Pediatric Pancreatitis: In Search of a Cure (INSPPIRE), it was reported that early-onset pancreatitis below 6 years of age was likely associated with genetic abnormalities, particularly PRSS1 (43%) or CTRC (14%) mutations." (PMID 33375361, 2020). "While mutations in the PRSS1 cause chronic pancreatitis on their own, the SPINK1 mutation is instead likely to act as a disease modifier, lowering the threshold for an individual developing pancreatitis from other genetic factors such as the CFTR mutations and environmental factors." (PMID 29515728, 2017). "More importantly, the model fails to explain how the other pancreatitis associated PRSS1 mutations might work, as the majority of these do not affect trypsin stability." (PMID 17204147, 2007). "Overaccumulation and misfolding of the serine protease 1 (PRSS1), also known as trypsinogen, have been established as key driving factors for the development of some types of pancreatitis, such as hereditary or idiopathic CP8,9." (PMID 31506423, 2019). "CP might cluster in families, and in many of these affected subjects as well as young patients without a family history of pancreatitis, mutations in the genes coding for cationic trypsinogen (PRSS1), pancreatic secretory trypsin inhibitor (SPINK1) and chymotrypsinogen C (CTRC) can be identified." (PMID 24260417, 2013). "As controls, Japanese patients with alcohol-unrelated pancreatitis carrying pathogenic variants in PRSS1 or SPINK1, as well as those without pathogenic variants in pancreatitis susceptibility genes, were enrolled." (PMID 41247519, 2025). "This guidance does not apply to those who have a PGV in PRSS1 but do not have a clinical phenotype of pancreatitis." (PMID 39932614, 2025). "While, the 2 patients with CF without pancreatitis had, in IPAT genes, a heterozygous PRSS1/PRSS2 hybrid mutation and a heterozygous missense mutation of CTRC, respectively." (PMID 30134826, 2018). "PRSS1 gene expression seems to induce apoptosis and to promote spontaneous pancreatitis and its role is not known in NSCLC." (PMID 27081700, 2016). "The pancreatitis in this patient was not due to gallstones or alcohol abuse, and analysis of genes known to be associated with pancreatitis, such as SPINK1, CFTR, PRSS1 and CTRC, did not reveal any mutations." (PMID 26082470, 2015). "In the setting of hereditary pancreatitis with a clinical pancreatitis phenotype, if this is caused by a PGV in PRSS1, all societies recommend surveillance regardless of family history beginning at age 40, or 20 years after the onset of the first episode of pancreatitis." (PMID 39932614, 2025).
hereditary pancreatitis (73 papers, 2006 to 2026). "Inborn mutations in the PRSS1 gene encoding human cationic trypsinogen cause hereditary pancreatitis." (PMID 41801884, 2026). "This risk is significantly higher in hereditary pancreatitis, with cumulative incidence reaching 19% and 12% by age 60 among patients with PRSS1 and SPINK1 mutations, respectively." (PMID 40722803, 2025). "Hereditary pancreatitis, often caused by PRSS1 mutations, is associated with chronic inflammation of the pancreas beginning in childhood." (PMID 40722803, 2025). "Variants in the PRSS1 gene, which encodes human cationic trypsinogen have been conclusively associated with autosomal dominant hereditary pancreatitis." (PMID 40861062, 2025). "The p.N29I, the second most common PRSS1 mutation, first described in 1997, accounts for nearly 25% of hereditary pancreatitis cases." (PMID 40861062, 2025). "Hereditary chronic pancreatitis (CP) is caused by risk alleles that increase the intrapancreatic activation of the digestive protease cationic trypsinogen (PRSS1) to its active form trypsin." (PMID 40067384, 2025). "Since the PRSS1 gene, which encodes human cationic trypsinogen, was first linked to autosomal dominant hereditary pancreatitis, more than 50 PRSS1 variants have been reported." (PMID 40861062, 2025). "The study demonstrated a diagnostic-yield for FPC (3%), PRSS1/SPINK1 (hereditary pancreatitis; 4%), CDKN2A (FM) (5%), BRCA1/2 and PALB2 (HBOC) (6.3%), and STK11/LKB1 (Peutz–Jeghers syndrome; PJS; 12.2%)." (PMID 38619782, 2024). "It is acknowledged that patients with hereditary pancreatitis or PRSS1 gene mutations face an increased risk of pancreatic cancer." (PMID 39896151, 2024). "Numerous analyses in the literature focus on familial pancreatitis, for which many significant genetic mutations have been successfully described, including those in the PRSS1 and SPINK1 genes." (PMID 39457082, 2024). "With the following specific exceptions: individuals with Peutz-Jeghers syndrome (STK11 mutation) from 35 years of age, FAMMM (CDKN2A mutation) from 40 years of age and Hereditary pancreatitis (PRSS1 mutation) from 40 years of age." (PMID 38753287, 2024). "Of those with hereditary pancreatitis, variants in the PRSS1 and SPINK1 genes were the most prevalent (16/22, 74% of individuals)." (PMID 39337011, 2024). "In case of hereditary pancreatitis caused by mutations in the PRSS1, CFTR, SPINK1 genes, pancreatectomy becomes advisable, including for prevention of pancreatic cancer." (PMID 39896151, 2024). "For example, among individuals with hereditary pancreatitis associated with PRSS1, a pilot study suggested clinical benefit from treatment with amlodipine." (PMID 39172977, 2024). "Pancreatectomy becomes advisable in case of proven idiopathic hereditary pancreatitis and identified mutations in the PRSS1, CFTR, SPINK1, or CTRC genes, especially when there is a risk of ductal adenocarcinoma." (PMID 39896151, 2024). "This cumulative risk is higher in hereditary pancreatitis: 19 and 12% in the case of PRSS1 and SPINK1 mutations, respectively, at an age of 60 years." (PMID 36765725, 2023). "In the specific context of hereditary pancreatitis due to the PRSS1 gene mutation, it is recommended that cancer screening be carried out from the age of 40." (PMID 36765725, 2023). "In the case of hereditary pancreatitis (HP), mutations in the PRSS1 gene appear in 80% of diagnoses, and the risk of developing pancreatic cancer compared to the general population in people with HP is high (RR = 69)." (PMID 37509296, 2023). "In hereditary pancreatitis (secondary to the PRSS1 gene mutation), the risk of cancer is much higher than in alcoholic CP." (PMID 36765725, 2023). "Hereditary pancreatitis is linked to a mutation in the PRSS1 gene which codes for the cationic trypsinogen." (PMID 36765725, 2023). "A rare form, hereditary pancreatitis, is consequent on autosomal dominant mutations in the gene for the cationic trypsinogen (PRSS1)." (PMID 36233433, 2022).
hereditary pancreatitis (continued). "In the Japan National Survey of Hereditary Pancreatitis, mutations in PRSS1 were found in 30 of 73 families (41.1%) and mutations in SPINK1 in 26 (35.6%)." (PMID 35994093, 2022). "Hereditary pancreatitis refers to acute recurrent or chronic pancreatitis caused by autosomal dominant variants in the PRSS1 gene (serine protease 1), SPINK1 (serine protease inhibitor kazal type 1), or other genes." (PMID 35163129, 2022). "The reduced penetrance of genes such as PRSS1 associated with hereditary pancreatitis indicates a role for novel inherited factors." (PMID 36699452, 2022). "In a study conducted by EUROPAC (European Registry of Hereditary Pancreatitis and Pancreatic Cancer) in 2004, which included 112 families with HP from 14 countries, mutations in PRSS1 gene were found in 81% of families included in the analysis." (PMID 35761384, 2022). "The most frequently found PRSS1 pathogenic variants belong to the trypsin-dependent pathway and cause hereditary pancreatitis with incomplete penetrance." (PMID 34065437, 2021). "Up to now, the best identified misfolding variants increasing CP risk or causing hereditary pancreatitis have been discovered in PRSS1 and CPA1 genes." (PMID 34065437, 2021). "Hereditary pancreatitis is a rare form which is mainly triggered by autosomal dominant mutations in the cationic trypsinogen gene (PRSS1)." (PMID 33430357, 2021). "Germline and somatic mutations in the PRSS1 gene are associated with hereditary pancreatitis, chronic pancreatitis, and pancreatic adenocarcinoma." (PMID 31822803, 2020). "The major cause of hereditary pancreatitis is the mutation in cationic trypsinogen (PRSS1), serine protease inhibitor Kazal 1 (SPINK1) and cystic fibrosis transmembrane conductance regulator (CFTR) genes." (PMID 32796685, 2020). "PRSS1 (serine protease 1) is a gene whose germline variants are implicated in hereditary pancreatitis and an increased risk of pancreatic ductal adenocarcinoma." (PMID 31487856, 2019). "Since the discovery that a genetic variant in PRSS1 (cationic trypsinogen) causes hereditary pancreatitis, most investigations to identify additional genetic risk factors focused on proteases and their inhibitors." (PMID 30408063, 2018). "Hereditary pancreatitis is a rare cause of chronic pancreatitis, with mutations in PRSS1, SPINK1, and CFTR genes being the most common genetic causes." (PMID 29515728, 2017). "Germline mutations in the protease serine 1 (PRSS1) gene are associated with hereditary pancreatitis." (PMID 28383487, 2017). "The most common cause of hereditary pancreatitis is an autosomal dominant form caused by mutations in the PRSS1 gene which account for up to 80% of cases." (PMID 29515728, 2017). "In autosomal dominant hereditary pancreatitis, the penetrance of the PRSS1 Arg122His mutation has been calculated to be 86 %, whereas that of PRSS1 Ala16Val is of the order of 55–65 %." (PMID 23820649, 2013). "Hereditary pancreatitis is generally described as an autosomal dominant gain-of-function disorder related to mutations in the cationic trypsinogen gene PRSS1, which has an 80% penetrance." (PMID 23409095, 2013). "An additional 8 potentially deleterious coding nonsynonymous missense SNPs were located in genes previously linked to disease, including rs1509309, a Cys206Ser mutation in serine protease 1 (PRSS1), a gene linked to hereditary pancreatitis." (PMID 23139751, 2012). "Mutations in PRSS1 (cationic trypsinogen gene) are the underlying cause for hereditary pancreatitis and mutations in SPINK1 (serine protease inhibitor Kazal type I) are often found in patients with chronic or acute forms of the disease." (PMID 22216129, 2011).
hereditary pancreatitis (continued). "Cationic trypsinogen (PRSS1) mutations are associated with hereditary pancreatitis, an autosomal dominant disease." (PMID 17069643, 2006). "PRSS1 mutations are strongly associated with hereditary pancreatitis." (PMID 40979245, 2025). "In 80% of hereditary pancreatitis, a genetic mutation in PRSS1 can usually be identified." (PMID 38730578, 2024). "In addition, individuals over 40 years old should be screened if they carry the CKDN2A and PRSS1 mutations in combination with hereditary pancreatitis, as well as people over age of 35 who have been diagnosed with Peutz–Jeghers syndrome." (PMID 37509296, 2023). "Chronic alcoholic pancreatitis displays a cumulative risk of pancreatic cancer estimated at 4% after 15 to 20 years, this risk being higher for hereditary pancreatitis with 19% and 12% in the case of PRSS1 and SPINK1 mutations, respectively, and at an age of 60 years." (PMID 36765725, 2023). "In addition, alterations in the activity of trypsinogen cause hereditary pancreatitis resulting from ER stress, such as mutations in the PRSS1 and SPINK1 genes." (PMID 34954140, 2022). "Therefore, most of heterozygous pathogenic variants of PRSS1 are regarded as a cause of hereditary pancreatitis with autosomal dominant inheritance." (PMID 34065437, 2021). "Notably, our results demonstrated that genetic predisposition toward chronic hereditary pancreatitis and pancreatic carcinogenesis, which involve PRSS1 and SPINK1, in BTC patients was associated with susceptibility to germline mutations." (PMID 33754015, 2021). "Hereditary pancreatitis associated with mutations in PRSS1, especially p.Arg122His, could considerably increase the risk of pancreatic adenocarcinoma (87 times more likely at age 55)." (PMID 34065437, 2021). "The A16V (C→T) mutation in PRSS1, which encodes a cationic trypsinogen and has a mutation associated with hereditary pancreatitis and pancreatic adenocarcinoma, was observed in 40% (8/20) (7/17 of ETV6 translocation-positive and 1/3 of ETV6 translocation-negative secretory carcinomas)." (PMID 31822803, 2020). "Mutations in the PRSS1 (serine protease 1) gene encoding human cationic trypsinogen cause hereditary pancreatitis or may be associated with sporadic chronic pancreatitis." (PMID 30792736, 2019). "Although gain-of-function mutations in gene for cationic trypsinogen (PRSS1) are well established in hereditary pancreatitis in patients of different ethnicity, previous studies in Indian patients with CP did not identify any significant mutations/polymorphisms in the PRSS1 gene." (PMID 26820620, 2016). "Indeed, starting with cationic trypsinogen gene (PRSS1) mutations in hereditary pancreatitis, mutations in many other genes predominantly SPINK1, CFTR, chymotrypsin C, CPA1, CEL etc. have been reported in patients with CP." (PMID 26820620, 2016). "Cationic trypsinogen (PRSS1) has several mutations which lead to chronic hereditary pancreatitis." (PMID 24474939, 2013). "Furthermore, more children were diagnosed with hereditary pancreatitis compared to adults (33.3% versus 8%; p < 0.001) and more children reported genetic mutations: PRSS1 mutations (29.2% vs. 6%), SPINK (25% vs. 3%), CFTR mutations (20.9% vs 6.5%) p values of < 0.001, < 0.001 and 0.014 respectively." (PMID 37432930, 2023). "Although the first case of hereditary pancreatitis (HP) was reported by Steinberg and Comfort in 1952, the PRSS1 gene was discovered as the gene responsible for Whitcomb 44 years later in 1996." (PMID 40230746, 2025). "PRSS1 and SPINK1 are associated with hereditary pancreatitis as well as PDAC and should be included in panels based on clinical features." (PMID 39860372, 2025). "This study also calculated the NNS for specific HRI groups, with a NNS of 250 for a PV in BRCA genes, 130 for PRSS1/SPINK1 (hereditary pancreatitis), 71 for STK11/LKB (PJS) and 51 for a PV in the CDKN2A gene." (PMID 38619782, 2024).
hereditary pancreatitis (continued). "Cationic trypsinogen (PRSS1) mutations are gain-of-function mutations that stimulate the autoactivation of the proform to trypsin, which are associated with autosomal dominant hereditary pancreatitis." (PMID 34436220, 2021). "The trypsinogen gene PRSS1, therefore, is in the first line of genes which are tested in patients with suspected hereditary pancreatitis (HP)." (PMID 33430357, 2021). "In the one extreme, rare gain-of-function missense or copy number variants in the PRSS1 gene (encoding cationic trypsinogen; MIM# 276000) can cause autosomal dominant hereditary pancreatitis." (PMID 33202925, 2020). "A relationship between a mutation in the cationic trypsinogen (protease serine 1, PRSS1) gene and hereditary pancreatitis (HP) was first identified in 1996." (PMID 33375361, 2020). "He underwent genetic testing for various genes known to cause hereditary pancreatitis: CASR, CFTR, CTRC, PRSS1, SPINK1." (PMID 29515728, 2017). "Gene conversion events between PRSS1 and PRSS2 or between PRSS1 and the pseudogene PRSS3P2 were shown to generate pathogenic alleles that cause hereditary pancreatitis." (PMID 27999401, 2016). "For hereditary pancreatitis, heterozygous variants in two mechanistically genes of ‘trypsin-dependent pathway’, PRSS1 (encoding cationic trypsinogen) and SPINK1 (encoding pancreatic secretory trypsin inhibitor products), are said to have the effect of occurring human pathogenic variants." (PMID 37813108, 2023). "As a diagnostic test, the NICE recommends MRI/MRCP or EUS in people without hereditary pancreatitis and CT in those with hereditary pancreatitis and a PRSS1 mutation." (PMID 37509296, 2023). "Individuals with an autosomal dominant history of hereditary pancreatitis but without identified mutation of PRSS1 are also to be included in this annual screening." (PMID 36765725, 2023). "These genes are either associated with non-life-threatening disorders (FLG; ichthyosis vulgaris), late-onset disorders (NOTCH3; cerebral autosomal dominant arteriopathy with sub-cortical infarcts and leukoencephalopathy, CADASIL) or risk factors for disease (PRSS1, CTRC; hereditary pancreatitis)." (PMID 36335097, 2022). "In common with many other diseases, the process of genetic discovery in CP began with the mapping and identification of a causative gene (i.e., PRSS1 (OMIM #276000; encoding cationic trypsinogen)) for a Mendelian form of the disease, autosomal dominant hereditary pancreatitis." (PMID 35974416, 2022). "Hereditary pancreatitis can be defined as a patient with recurrent acute or chronic pancreatitis who has a first or second degree relative having similar presentation or one who presents with mutated SPINK1, PRSS1, CFTR, and CTRC genes." (PMID 31588422, 2019). "Gain-of-function PRSS1 (encoding cationic trypsinogen; MIM #276000) missense mutations were first reported in individuals with ICP in 1999, three years after the identification of PRSS1 as a causative gene for hereditary pancreatitis." (PMID 23951356, 2013). "Genetic testing for PRSS1 and SPINK1 in patients with hereditary pancreatitis has been reported in Europe and the US." (PMID 35994093, 2022).